KRTAP4-11 (keratin associated protein 4-11)
Description:
In the hair cortex, hair keratin intermediate filaments are embedded in an interfilamentous matrix, consisting of hair keratin-associated proteins (KRTAP), which are essential for the formation of a rigid and resistant hair shaft through their extensive disulfide bond cross-linking with abundant cysteine residues of hair keratins. The matrix proteins include the high-sulfur and high-glycine-tyrosine keratins.
Synonyms: KAP4.14; KRTAP4-14; KRTAP4.14; KAP4.11
Tractability: No criterion of Open Targets' tractability assessment is met for any kind of drug.
Gene: Protein-coding gene on chromosome 17 (41,117,181 to 41,118,373, reverse strand). Ensembl gene ENSG00000212721.
Pathways (Reactome):
Developmental Biology: Keratinization
Gene Ontology:
Molecular function: protein binding
Biological process: hair cycle
Cellular component: cytosol; keratin filament
Genetic constraint (gnomAD): Loss-of-function variants: 5 observed, 4.56 expected, observed/expected ratio (o/e) 1.1, 90% interval 0.56 to 1.85. That is too few expected variants to judge how well the gene tolerates losing a copy. Missense variants: 242 observed, 224.92 expected, observed/expected ratio (o/e) 1.08, 90% interval 0.97 to 1.2. Synonymous variants: 92 observed, 74.56 expected, observed/expected ratio (o/e) 1.23, 90% interval 1.04 to 1.47.
Homologues: Orthologues: chimpanzee KRTAP4-11 (96% identical), mouse Krtap5-24 (46% identical), mouse Krtap5-26 (42% identical), mouse Krtap5-2 (39% identical), rat Krtap5-8 (38% identical), rat AABR07006049.1 (38% identical), mouse Krtap5-20 (36% identical). Paralogues in human: KRTAP4-9 (91% identical), KRTAP4-8 (86% identical), KRTAP4-6 (81% identical), KRTAP4-12 (79% identical), KRTAP4-5 (77% identical), KRTAP4-7 (70% identical), KRTAP4-3 (66% identical), KRTAP4-4 (64% identical), KRTAP4-16 (61% identical), KRTAP4-2 (55% identical), KRTAP4-1 (50% identical), KRTAP10-7 (48% identical), and 35 more.